MEG3 (maternally expressed 3)
Diseases named in the same sentence as MEG3 in open-access papers (continued):
Sharing a sentence is not in itself a finding about the gene and the disease.
glioblastoma (14 papers, 2020 to 2025). The most malignant astrocytic tumor (WHO grade IV). "However, the mechanism underlying the reduced MEG3 expression in the glioblastoma cells is unclear." (PMID 35860793, 2022). "Maternally expressed gene 3 (MEG3), recognized as a tumor suppressor lncRNA, is downregulated across various cancer types, including glioblastoma." (PMID 39015773, 2024). "Neither 5FU nor Nvtx was found to be effective in reducing the cell viability of MEG3 suppressed and overexpressed patient derived glioblastoma cells." (PMID 37525401, 2023). "We compared the expression of MEG3 in the glioblastoma cell line U-251MG with noncancer cells HAs and TECs and found that the mRNA level of MEG3 in the glioblastoma cells is significantly downregulated." (PMID 35860793, 2022). "At the same time, chemoresistance was created by silencing MEG3 using si-RNA, and the authors discovered that MEG3 is a critical tool for tracking chemotherapy response in glioblastoma." (PMID 35619711, 2022). "Other studies have shown that the MEG3 promoter is hyper-methylated by DNMT1 in glioblastoma tissue, and, therefore, this gene is completely silenced." (PMID 32283739, 2020). "In glioblastoma, several studies indicate participation of MEG3 in the pathogenesis and development of this disease." (PMID 32283739, 2020). "In this study, we show that MEG3 is downregulated in the glioblastoma cells and overexpression of MEG3 could inhibit the growth and reduce the migration and invasion ability of the glioblastoma cell line U-251MG." (PMID 35860793, 2022). "As an important imprinted gene, the copy number variation (CNV) of MEG3 in both glioblastoma multiforme (GBM) and low-grade glioma (LGG) were analyzed using GSCALite database, whereas its prognostic significance was assessed using PrognoScan and GEPIA databases." (PMID 34220951, 2021). "Taken together, these findings suggest that MEG3 may function as a prognostic marker and a potential target for glioblastoma therapy." (PMID 32283739, 2020). "In glioblastoma, HLA-F-AS1 binds to MEG3, promoting invasion and migration while inhibiting apoptosis." (PMID 40350996, 2025). "In glioblastoma (GBM), lncRNA MEG3 acts as a tumor suppressor and its low expression is significantly related to the short survival of GBM patients." (PMID 33898430, 2021). "Moreover, epigenetic alterations, particularly hypermethylation within the MEG3-DMR region, predominantly drive the downregulation of genes within the DLK1-DIO3 locus in glioblastoma." (PMID 39015773, 2024). "Suppression of the MEG3 gene in patient‐derived oligodendroglioma cells also showed the same effect whereas glioblastoma cell proliferation and chemosensitivity were not affected by MEG3 inhibition." (PMID 37525401, 2023). "Additionally, MEG3 acts as a ceRNA to miR-19a, which represses PTEN expression, leading to glioblastoma cell proliferation, migration, and invasion." (PMID 32283739, 2020).
Insulin resistance (14 papers, 2016 to 2025). Increased resistance towards insulin, that is, diminished effectiveness of insulin in reducing blood glucose levels. "The lncRNA MEG3 has also been implicated not only in insulin resistance but also in ocular diseases." (PMID 39529988, 2024). "Gtl2/Meg3 deficiency induces cellular senescence of hepatic vascular endothelium and impairs glucose homeostasis and insulin resistance in obesity." (PMID 38521877, 2024). "Meg3 is a known imprinted tumor suppressor gene and was recently implicated in hepatic insulin resistance." (PMID 27623010, 2016). "In this context, due to its positive regulatory role, a decrease in the level of lncRNA MEG3 may contribute to AD progression, which is closely linked to T3D, by affecting brain insulin resistance." (PMID 40869265, 2025). "In insulin-resistant (IR) children, MEG3, ATF4, FTO, ACACA, and SREBP1 were reduced, while FASN was increased." (PMID 40806129, 2025). "NAFLD patients frequently present insulin resistance, which promotes the reactivation of MEG3 to maintain glucose homeostasis." (PMID 36979495, 2023). "Unfortunately, up to this point, no data concerning the specificity and sensitivity of circulating MEG3 in cases of hepatic insulin resistance have been published." (PMID 32545342, 2020). "Several studies have demonstrated that Meg3 promotes insulin resistance by serving as a ceRNA of miRNAs, to upregulate mRNA expression and consistently, Meg3 knockdown alleviates insulin resistance in palmitate-treated hepatocytes and in mice fed an HFD." (PMID 32614631, 2020). "MEG3 aggravated palmitate-induced insulin resistance by regulating miR-185-5p/Egr2 axis as a ceRNA in insulin-resistant hepatocytes." (PMID 33224264, 2020). "Also, our results disagree with an animal study that described that lncRNA MEG3 aggravates chronic inflammation and insulin resistance in adipocytes by stimulating TLR4/NF-KB while its downregulation had the reverse actions." (PMID 38985298, 2024). "MEG3 enhances hepatic insulin resistance via miR-214/ATF4 axis." (PMID 31195367, 2019). "Meg3 has been shown to serve as a ceRNA to regulate the miR-302a-3p-CRTC2 axis and the miR-214-ATF4 axis, and promote hepatic insulin resistance." (PMID 32614631, 2020).
pituitary adenomas (14 papers, 2005 to 2022). "Loss of GTL2/MEG3 is seen in many tumor types, including human pituitary adenoma, brain tumors, and liver tumors." (PMID 24970160, 2013). "Furthermore, Meg3 is downregulated in nonfunctional pituitary adenoma, and the decreased levels are associated with increased tumor invasive abilities." (PMID 28423647, 2017). "Based on the observation that MEG3 expression is lost in clinically nonfunctioning pituitary adenomas, we identified MEG3 as a tumor suppressor." (PMID 33722609, 2021). "highlighted a higher expression of MEG3 in GH-secreting pituitary adenomas with respect to non-functioning pituitary adenomas, where the expression was lost in most samples." (PMID 34484116, 2021). "In malignant tumor-related diseases, MEG3 and miR-376b are downregulated in patients with clinically nonfunctioning pituitary adenomas." (PMID 33083454, 2020). "For example, MEG3 expression was significantly lower in non-functional pituitary adenoma compared to normal tissue." (PMID 28407691, 2017). "Moreover, downregulation of noncoding MEG3 and HOX genes has been associated with the development of non-functional pituitary adenomas and parathyroid tumors, respectively." (PMID 33384663, 2020). "In non-cardiac cells, Gtl2/Meg3 has been hypothesized to function as a tumor suppressor given its reduced expression in a variety of tumors including pituitary adenomas." (PMID 29996488, 2018).
Sepsis (14 papers, 2019 to 2025). Sepsis is defined as life-threatening organ dysfunction caused by a dysregulated host response to infection. "lnc-MEG3 (AUROC: 0.887) and the lnc-MEG3/miR-21 ratio (AUROC: 0.934) had high values for predicting elevated sepsis risk, while miR-21 (AUROC: 0.801) gave excellent predictive value for a reduced sepsis risk." (PMID 34991675, 2022). "Overexpression of lncRNA MEG3 is associated with high mortality rates in patients with sepsis, thus is indicative of poor clinical outcomes and is believed to be associated with LPS-induced renal epithelial cell and cardiomyocyte apoptosis." (PMID 34041287, 2021). "The upregulation of MEG3 disrupted the intestinal injury caused by sepsis." (PMID 32410866, 2020). "The expression level of lncRNA MEG3 is significantly reduced in patients with sepsis, and this reduction has prognostic significance." (PMID 38473915, 2024). "Long non-coding RNA maternally expressed gene 3 (lnc-MEG3), and the lnc-MEG3/miR-21 axis were increased, while miR-21 expression was decreased in sepsis patients compared with healthy controls." (PMID 34991675, 2022). "In our present study, we investigated the biological function of MEG3 in sepsis, especially during the intestinal injury." (PMID 32410866, 2020). "Then, to assess the effects of MEG3 on intestinal mucosal injury, MEG3 was restored in sepsis mice via infecting LV-MEG3 into the mice." (PMID 32410866, 2020). "Then, MEG3 was overexpressed, and we found that its overexpression repressed the intestinal injury via downregulating miR-129-5p in sepsis mice." (PMID 32410866, 2020). "It has been reported MEG3 can regulate IL-1β abundance to prevent sepsis during lung infection by acting as a decoy of miRNA." (PMID 32410866, 2020). "Here, we reported miR-129-5p was upregulated in sepsis and it was negatively correlated with MEG3 expression." (PMID 32410866, 2020). "We observed that IL-6 and TNF-α were induced in sepsis mouse models and MEG3 was able to restrain their protein levels." (PMID 32410866, 2020). "miR-129-5p was elevated in sepsis, and miR-129-5p was able to reverse the effects of MEG3 in sepsis." (PMID 32410866, 2020). "This suggests that the reduced MEG3 expression may exacerbate sepsis by increasing inflammation and inhibiting apoptosis in macrophages." (PMID 38473915, 2024). "Furthermore, the ratio of lncRNA maternally expressed gene 3 (lnc-MEG3) to lnc-MEG3/miR-21 serves as a robust indicator of increased sepsis vulnerability, whereas miR-21 presents as a reliable marker for decreased sepsis susceptibility." (PMID 39201697, 2024). "Further research is needed to elucidate MEG3’s role in sepsis." (PMID 38473915, 2024). "Moreover, existing evidence suggests that lncRNA MEG3 can be carried by EVs, while MEG3 is poorly-expressed in LPS-induced intestinal injury in sepsis." (PMID 34895044, 2021). "Low expression of lnc-MEG3 might also serve as a potential biomarker for the development, progression, and prognosis prediction of sepsis." (PMID 34041287, 2021). "Several studies have suggested that lncRNA maternally expressed gene 3 (MEG3) might serve as a valuable indicator for the progression of sepsis, providing new strategy against acute respiratory distress syndrome in sepsis." (PMID 34630395, 2021). "These suggested MEG3/miR-129-5p/SP-D was involved in sepsis-induced intestinal injury." (PMID 32410866, 2020). "Currently, we investigated the role of MEG3/miR-129-5p/SP-D in sepsis." (PMID 32410866, 2020). "We hypothesized MEG3 was involved in LPS-induced intestinal injury in sepsis by modulating miR-129-5p and SP-D." (PMID 32410866, 2020). "Nevertheless, the molecular roles of MEG3 in sepsis remain further illustrated." (PMID 32410866, 2020).
Sepsis (continued). "Currently, we found MEG3 was decreased in sepsis mice and LPS-incubated cells." (PMID 32410866, 2020). "In conclusion, we indicated that sepsis-triggered intestinal injury might be the dysregulation of MEG3, miR-129-5p, and SP-D." (PMID 32410866, 2020). "MEG3 was recently reported to bind miR‐138 and derepress IL‐1β, intensifying the reaction of macrophages to bacterial infections of the lung and preventing sepsis." (PMID 31496026, 2019). "Whether MEG3 could function as a ceRNA to regulate sepsis progression is barely known." (PMID 32410866, 2020). "One such lncRNA, namely lncRNA maternally expressed 3 (lncRNA MEG3), an imprinted lncRNA located at chromosome 14q32, has been previously identified to alleviate lipopolysaccharide (LPS)-induced intestinal injury in sepsis." (PMID 34895044, 2021). "MEG3 restrained the activation of TNF-α and IL-6, in sepsis models." (PMID 32410866, 2020).
Cerebral ischemia (13 papers, 2016 to 2024). Restriction of arterial blood supply to the brain associated with insufficient oxygenation to support the metabolic requirements of the tissue. "Alternatively, long non-coding RNA MEG3 (lncRNA MEG3) expression increases during cerebral ischemia, and the downregulation of lncRNA MEG3 expression activates Wnt/β-catenin signaling and promotes neurogenesis." (PMID 38185705, 2024). "Long noncoding RNA MEG3 promotes cerebral ischemia‒reperfusion injury by targeting the miR-485/AIM2 axis to increase pyroptosis." (PMID 38102696, 2023). "Down-regulation of MEG3 can reduce cerebral ischemia-reperfusion pyroptosis and neuroinflammation through the miR-485/AIM2 signaling pathway, down-regulate the expression of AIM2 in the inflammasome." (PMID 36275741, 2022). "In a cerebral ischemia-reperfusion model, MEG3 expression is elevated and is considered to be an injury factor." (PMID 36275741, 2022). "Down-regulation of MEG3 can reduce cerebral ischemia-reperfusion-induced injury by regulating miR-21/PDCD4 and improve neurobehavioral function in MCAO/R mice." (PMID 36275741, 2022). "Accordingly, above data seems to point to the potential of MEG3–miR-21–PDCD4 interaction in the treatment of cerebral ischemia." (PMID 29238035, 2017). "Our data described a global time dependent analysis of the levels of hippocampal MEG3 and miR-181b during cerebral ischemia and in OGD-cultured hippocampal HT22 cell line in periods of 6, 12, and 24 h post hypoxia condition." (PMID 27642276, 2016). "Interestingly, MEG3 overexpression exacerbates cerebral ischemia-reperfusion injury, but improves cognitive impairment and alleviates pathological damage in AD patients." (PMID 36895559, 2023). "The lncRNA MEG3 promotes cerebral ischemia-reperfusion injury by increasing pyroptosis." (PMID 37156816, 2023). "Ultimately, MEG3 knockdown reduces neuroinflammation to alleviate cerebral ischemia-reperfusion." (PMID 36275741, 2022). "By targeting miR-485/AIM2 axis, MEG3 promotes cerebral ischemia/reperfusion injury." (PMID 35256601, 2022). "Moreover, Liang and colleagues have indicated AIM2 as a direct target of miR-485 and postulated that the long non-coding RNA MEG3 promotes cerebral ischemia-reperfusion injury by increasing pyroptosis by targeting the miR-485/AIM2 axis." (PMID 32645874, 2020). "Therefore, our present study evaluated the interacting epigenetic change of lncRNA MEG3 to miR-181b in focal cerebral ischemia injury of mice subjected to middle cerebral artery occlusion (MCAO)." (PMID 27642276, 2016).
Cognitive impairment (13 papers, 2021 to 2025). Abnormal cognition is characterized by deficits in thinking, reasoning, or remembering. "Upregulation of MEG3, by regulating insulin signaling in the brain, may offer neuroprotective effects and potentially alleviate cognitive impairment and neuronal damage associated with AD pathogenesis." (PMID 40869265, 2025). "In the AD rat model, the intervention of MEG3 improves cognitive impairment, alleviates neuronal damage and inhibits astrocyte activation in hippocampus tissues in AD by inactivating the PI3K/Akt signaling pathway." (PMID 36875702, 2023). "This literature help assemble a knowledge base of Meg3 in hippocampal function, but more effort need to be made to characterize the functional implication of Meg3 in interneurons for cognitive impairment and epileptic seizure of anti‐NMDAR encephalitis." (PMID 36942475, 2023). "Previous studies have reported the potential therapeutic effects of MEG3 in AD, as overexpression of MEG3 was shown to improve cognitive disorders, reduce nerve damage, and inhibit astrocyte activation in the hippocampal tissues by inhibiting the PI3K/Akt signaling pathway in rats." (PMID 37799732, 2023). "Interestingly, previous studies have correlated the MEG3 upregulation with improved cognitive impairment and protection against apoptosis in an AD rat model, enhancing spatial learning and memory capability." (PMID 38027526, 2023). "Also, upregulation of MEG3 led to improved cognitive impairment, reduced neuronal damage, reduced Aβ positive expression, and inhibits activation of astrocytes in hippocampus tissues in AD rats via inactivation of the PI3K/Akt signaling pathway." (PMID 34621163, 2021). "A decline in the expression of lncRNA maternally expressed 3 (MEG3) and maternally expressed 8 (MEG8) has been reported in PD individuals, which is strongly correlated with non-motor symptoms, cognitive deficit, and inflammation, respectively." (PMID 38790711, 2024).
diabetic retinopathy (12 papers, 2019 to 2025). "Nevertheless, in the last decade, limited research has investigated the underlying molecular mechanism of MEG3 in diabetic retinopathy." (PMID 32519748, 2020). "A previous study suggested that a low level of lncRNA MEG3 participates in ocular angiogenesis in diabetic retinopathy, and another study has mentioned neovascularisation as one of the most common features in BD patients." (PMID 38985298, 2024). "It was reported that the upregulation of MEG3 led to the downregulation of miR-34a (the miRNA responsible for the inflammatory response and apoptosis in diabetic retinopathy)." (PMID 36297381, 2022). "MEG3 could alleviate diabetic retinopathy by forming a competing endogenous RNA (ceRNA) network with miR-34a." (PMID 36297381, 2022). "However, in an experimental diabetic retinopathy cell model, melatonin delays diabetic retinopathy (DR) progression by upregulating MEG3 and inhibiting model cell activation and pro-inflammatory cytokine production via the MEG3/miR-204/SIRT1 axis." (PMID 36267400, 2022). "The high-glucose conditions suppress the expression of lncRNA MEG3, whereas the rescue of MEG3 could delay diabetic retinopathy by inhibiting TGF-1 and VEGF levels." (PMID 32190702, 2020). "The aim of the study was to demonstrate how transthyretin (TTR) could affect long non-coding RNA (lncRNA) of maternally expressed gene 3 (MEG3) and play important roles in diabetic retinopathy (DR)." (PMID 31847264, 2019). "Also, Zhang et.al (2018) concluded that lncRNA MEG3 overexpression may inhibit the development of diabetic retinopathy by inhibiting TGF-β1 and VEGF expression." (PMID 34284789, 2021). "Previous studies have validated the function of Meg3 related to its methylation and the PI3K/Akt/mTOR signalling pathway in diabetic retinopathy." (PMID 34717547, 2021). "They demonstrated that the overexpression of lncRNA MEG3 may inhibit the expression of TGF-β1 and VEGF to ameliorate diabetic retinopathy, which suggests the up-regulation of the lncR MEG3 as a promising therapy for diabetic vascular complications." (PMID 34349728, 2021).